EGFR (epidermal growth factor receptor)
Diseases named in the same sentence as EGFR in open-access papers (continued):
Sharing a sentence is not in itself a finding about the gene and the disease.
lung cancer (continued). "In the present study, combined therapy consisting of gefitinib and fulvestrant led to enhanced anti-proliferative activity in EGFR-mutant lung cancer cells and improved PFS in adenocarcinoma patient with an EGFR mutation." (PMID 26096604, 2015). "In a retrospective study of 118 patients with bone metastasis from lung cancer, treatment with an epidermal growth factor receptor (EGFR) inhibitor indicated improved prognosis for patients with adenocarcinoma." (PMID 25452785, 2015). "Specifically, we found that ectopic expression of EGFR-L858R in lung cancer cells acted through activation of ERK signaling pathways to induce the expression of CXCR4." (PMID 26338423, 2015). "Epidermal growth factor receptor (EGFR) overexpression and chromosome 3p deletion are 2 frequent events in lung cancers." (PMID 26632716, 2015). "For the lung cancer cells harboring EGFR T790M, all EGFR-TKIs, but erlotinib, effectively inhibited the phosphorylation of EGFR, AKT, and ERK." (PMID 26515464, 2015). "To verify that these tumors recapitulated tumors observed in patients, we treated the mice with erlotinib, an FDA-approved EGFR inhibitor widely used in the treatment of lung cancer." (PMID 26573149, 2015). "The high prevalence of activating EGFR mutations (32.7%) and ALK rearrangements (6.8%) among lung cancer patients in China has further expanded the use of these targeted agents." (PMID 26220301, 2015). "In human lung cancer cell lines harboring either the wildtype or mutant EGFR, it was reported that Shp2 and Erk1/2 were less active in cells harboring mutant EGFR." (PMID 25730908, 2015). "Here, we describe a new mouse model of aggressive papillary ear tumor that was serendipitously discovered during the generation of a mouse model for mutant EGFR-driven lung cancer." (PMID 26027747, 2015). "However, positive trial results from lung cancer patients with EGFR activating mutations treated with EGFR inhibitors suggest it may be worthwhile to identify BC patients with similar EGFR mutations and treat them in modern studies aiming at precision medicine." (PMID 26267891, 2015). "Recently, Bivona and colleagues provided evidence of the involvement of NF-κB in modulating lung cancer dependence upon EGFR oncogenic signaling and consequently in resistance to erlotinib." (PMID 26015408, 2015). "There are still few studies addressing the mechanism of IGF1R activation in EGFR-TKIs resistance in lung cancer cells." (PMID 26554308, 2015). "Through transfection with different ERβ isoforms, EGFR mutant lung cancer cells with c-ERβ and n-ERβ co-expression (PC9/ERβ1) or only c-ERβ expression (PC9/ERβ2 and PC9/ERβ5) were constructed as in vitro models." (PMID 26096604, 2015). "EGFR overexpression is detected in many epithelial cancers including lung cancer, colorectal cancer, head and neck cancer, and HCC." (PMID 26436086, 2015). "During the generation of a mouse model for mutant EGFR-driven lung cancer, we serendipitously discovered a new genetically engineered mouse (GEM) model of aggressive papillary ear tumor." (PMID 26027747, 2015). "Icotinib, which has a clinical efficacy similar to that of gefitinib but less adverse effects, is approved for the treatment of EGFR-mutant lung cancer in China." (PMID 26134262, 2015). "The lung cancer cell lines used included PC-9 (EGFR exon 19del), H3255 (EGFR L858R), PC-9ER (EGFR exon 19 del+T790M), and H1975 (EGFR L858R+T790M)." (PMID 26515464, 2015). "The second example is an application from Cancer Systems Biology: we investigate the robustness of the EGFR IGF1R pathway in lung cancer." (PMID 26482604, 2015). "In Met-amplified lung cancer cells, activation of EGFR signaling contributes to the development of drug resistance after prolonged inhibition of the Met receptor." (PMID 25946048, 2015). "HDACis can reverse resistance to EGFR-TKIs through induction of E-cadherin expression in lung cancer cells." (PMID 25552401, 2015).
lung cancer (continued). "Lung cancer presents with the characteristics of frequent aberrance in driver genes, particularly the epidermal growth factor receptor (EGFR) gene." (PMID 26622796, 2015). "Both gefitinib and erlotinib are the first choice for therapy in lung cancer patients whose tumors harbor EGFR mutations and are reported to significantly prolong progression-free survival (PFS) in patients with EGFR-mutant lung cancer." (PMID 26134262, 2015). "Ectopic expression of EGFR-L858R in lung cancer cells acted through activation of ERK signaling pathways to induce the expression of CXCR4." (PMID 26338423, 2015). "Our data suggest that the EGFR-L858R mutant promotes the expression of CXCR4 in lung cancer cells primarily through the ERK signaling pathway, rather than PI3K-AKT and JAK-STAT3 pathways, thereby increasing invasive ability." (PMID 26338423, 2015). "In a recent study it has been reported that in cellular lung cancer models of acquired resistance to the EGFR TKI erlotinib there was an increased activation of AXL and induction of an EMT-like state." (PMID 25966280, 2015). "The approach following progression on a first-line EGFR TKI has been rapidly evolving together with the novel drug therapies and advances in the understanding of EGFR mutated lung cancers." (PMID 26371045, 2015). "In conclusion, EGFR-TKIs, such as gefitinib, are known to treat lung cancers with significant efficacies." (PMID 25807554, 2015). "Based on these promising results, it is suggested that orthopedic oncologists consider the combination of radiation and EGFR inhibitor therapy with surgery for the treatment of lung cancer metastasis to the spine." (PMID 25452785, 2015). "Osimertinib and rociletinib are 3rd generation EGFR-TKIs, both of which are reported to be effective in lung cancer cells harboring EGFR T790M in preclinical models." (PMID 26515464, 2015). "NSCLC represents approximately 80% of lung cancer cases, and over 60% of these tumors express the epidermal growth factor receptor (EGFR), rendering it a primary protein of interest of different targeted therapeutic approaches." (PMID 25853010, 2015). "Resent advances in understanding the molecular basis of lung cancer has led to practical implementation of epidermal growth factor receptor (EGFR)-targeted treatment." (PMID 25591975, 2015). "The mutated genes are often involved in controlling the growth of cells, such as two genes called EGFR and KRAS, which are associated with forms of lung cancer." (PMID 26047463, 2015). "Commonly observed aberrations in epidermal growth factor receptor (EGFR) signaling have led to the development of EGFR-targeted therapies for various cancers, including non–small cell lung cancer (NSCLC)." (PMID 25962919, 2015). "The results of cell invasion assay also revealed that transiently transfected EGFR-L858R mutant in CL1-0 lung cancer cells can promoted the lung cancer invasion ability (P < 0.01)." (PMID 26338423, 2015). "The detection of EGFR mutations by SABER was developed from cell line and validated in lung cancer xenograph model and clinical sample." (PMID 26448936, 2015). "The majority of patients with EGFR-mutant lung cancers eventually develop acquired resistance to EGFR-TKIs." (PMID 26160838, 2015). "It is known that activating mutations in the HRAS homolog, KRAS, decrease gefitinib sensitivity in NSCLC, and that activation of the PIK3CA pathway also reduces tyrosine kinase inhibitor sensitivity in EGFR-mutant lung cancers." (PMID 25969993, 2015). "In nonsmall cell lung cancer (NSCLC), EGFR mutations cluster around the ATP-binding pocket (exons 18–21) and some of these mutations activate the kinase and induce an increased sensitivity to EGFR-tyrosine kinase inhibitors." (PMID 26436086, 2015). "The use of EGFR TKIs is the standard of care in advanced/metastatic NSCLC with activating EGFR mutations, however their role in early-stage lung cancer is far less defined." (PMID 26308162, 2015).
lung cancer (continued). "In our previous study, we showed that the epidermal growth factor receptor (EGFR) inhibitors gefitinib and erlotinib both induced autophagy in lung cancer cells." (PMID 26384345, 2015). "The inhibition of autophagy increased the sensitivity of lung cancer cells to EGFR inhibitors, which suggests a novel approach for the enhancement of targeted therapy for lung cancer." (PMID 26384345, 2015). "Nevertheless, it is unclear if Shp2 is activated by oncogenic EGFR mutants in lung carcinoma or if inhibiting the Shp2 PTP activity can suppress EGFR mutant-induced lung adenocarcinoma." (PMID 25730908, 2015). "We also appreciate that Dr. Yi-Rong Chen kindly provided the human lung carcinoma cell lines, H1299-EGFR-WT (overexpressing EGFR-WT) and H1299-EGFR-L858R (overexpressing EGFR-L858R)." (PMID 26338423, 2015). "At the molecular level, all lung carcinomas showing diffuse overexpression of p16Ink4A and harboring genetic alterations involving EGFR and ALK had an excellent outcome, as represented in S2 Table." (PMID 26674347, 2015). "In turn, in the human lung carcinoma cell line A549 vanadium compounds enhance the expression of COX2 by the activation of the epidermal growth factor receptor (EGFR)." (PMID 26053397, 2015). "The EGNP released DOX in a sustained manner and effectively internalized in EGFR overexpressing A549 and H226 lung cancer cells via a receptor-mediated endocytosis." (PMID 25266303, 2014). "In our study, CX-4945 induced autophagosomes more potently than rapamycin, a well-known mTOR inhibitor in EGFR-mutant, lung cancer cells with T790M." (PMID 25486409, 2014). "ID1 exerts its function by acting as dominant negative transcriptional repressors of bHLH factors; we found that ID1 is up regulated in response to nicotine and EGF via nAChR and EGFR in various lung cancer cell lines." (PMID 25028095, 2014). "In summary, we have successfully developed EGF-surface modified gelatin nanoparticles to target EGFR overexpressing lung cancers." (PMID 25266303, 2014). "Agents targeting vascular endothelial growth factor and epidermal growth factor receptor (EGFR) mimic several novel targeted approaches that improve survival in patients with lung cancer." (PMID 25360163, 2014). "Targeting EGFR has led to a breakthrough in understanding of lung cancer biology, and the NSCLC treatment paradigm." (PMID 25505733, 2014). "A comparison of this gene list with our previous data identifying gene changes upon EGFR inhibition in EGFR-dependent lung cancer cells showed a remarkable overlap between the significantly modulated genes in the two independent experiments." (PMID 25238247, 2014). "The survey of this study specifically examined the diffusion of EGFR and ALK tests as the two main diagnostic lung cancer tests according to the relevant guidelines." (PMID 25562146, 2014). "EGFR is a particularly promising molecular target of therapy, as EGFR inhibitors have been widely applied to a variety of solid tumors, such as lung cancer, colorectal cancer, breast cancer, and even ESCC." (PMID 25153136, 2014). "As the majority of patients with lung cancer receiving EGFR-TKI therapy acquire resistance, repeated biopsies and detection of the EGFR mutation state are beneficial for selecting appropriate treatments." (PMID 25120654, 2014). "The existing quinazoline derivative based drugs used for treating lung cancer that inhibits the wild type of EGFR." (PMID 24992720, 2014). "AZD9291 is another new inhibitor of EGFR including T790M variant in clinical development (NCT01802632) and has already produced partial responses in patients that progressed on other EGFR inhibitors (15th World Conference on Lung Cancer, 2013)." (PMID 24722523, 2014). "These mesenchymal-like carcinoma cells have been shown to be resistant to many conventional lung cancer therapies, including taxanes, pemetrexed, gemcitabine, and EGFR TKIs." (PMID 25538889, 2014).
lung cancer (continued). "Either ligand-independent or ligand-induced EGFR phosphorylation was inhibited in lung cancer cells that strongly expressed DDX3X." (PMID 25343452, 2014). "Inhibition of the STAT3 pathway has been shown to overcome resistance of lung cancer, head and neck cancer, pancreatic cancer, and glioma to anti-EGFR therapy." (PMID 24662938, 2014). "Among the investigated substances, we determined that hinokitiol, from the essential oil of Calocedrus formosana heartwood, had the most potent anticancer effects on EGFR-TKI-resistant lung cancer cell lines (H1975 and PC9-IR)." (PMID 25105411, 2014). "Although surgical resection remains standard treatment for early stage non–small-cell lung cancer (NSCLC), it is now essential to confirm the status of epidermal growth factor receptor (EGFR) gene mutations when planning treatment strategies." (PMID 25152277, 2014). "With the development of molecular subtype in lung cancer, NSCLC patients with EGFR-WT had been identified to carry several new “driver mutations”, including KRAS, HER2, and BRAF mutations, as well as ALK, ROS1, and RET gene fusion." (PMID 25277203, 2014). "Cetuximab-induced nuclear localization of EGFR has been reported and poor response to Cetuximab was observed in lung cancer and other solid tumors correlating with EGFR nuclear localization thus making nuclear EGFR an important molecular target in cancer." (PMID 25238453, 2014). "Our present study revealed novel characteristics of afatinib-resistant sublclones established from the drug-sensitive lung cancer cell line PC9 harboring the activated deletion E746-A750 mutant EGFR." (PMID 25115383, 2014). "In recent years, epidermal growth factor receptor (EGFR)-targeted therapy has emerged as a novel and effective strategy in lung cancer management with major benefits in patients with EGFR activating mutations." (PMID 25215536, 2014). "Another study showed that miR-7 downregulates EGFR mRNA in different cancer cell lines, including lung cancer." (PMID 25593996, 2014). "More recently, gemcitabine, an inhibitor of epidermal growth factor receptor signaling, has been used to treat lung cancer patients." (PMID 25477992, 2014). "Cytohesins over expression enhances EGFR signaling in human lung cancers, whereas the chemical inhibition or knockdown of cytohesins reduces EGFR activation." (PMID 24618737, 2014). "Six trials reported HRs for PFS of EGFR M− lung cancer and 2 reported HRs for OS of EGFR M− lung cancer." (PMID 25029199, 2014). "This was in accordance with several preclinical studies which enrolled a panel of different lung cancer cell lines treated with chemotherapy/EGFR-TKI and reported that the sequence of chemotherapy→EGFR-TKI had advantage over other modalities." (PMID 25474307, 2014). "The results of this pooled analysis highlight the idea that the exon 19del mutation is a better indicator of strong efficacy in EGFR TKI treatment, which is an improvement over findings in patients with lung cancer that have been reported previously." (PMID 24908327, 2014). "Finally, the clinical and therapeutic approaches of lung cancer have had great advances over the last few decades by means of translational studies that identified predictive biomarkers already established in clinical practice, such as the of EGFR mutation and the of ALK-EML4 fusion." (PMID 25628210, 2014). "The EGFR double mutant lung cancer cell line NCI-H1975 is used to construct lung cancer xenograft models." (PMID 25539607, 2014). "Major splicing changes were observed, including in HER1/EGFR pre-mRNA, which were also seen in human lung cancer samples over-expressing the SRSF2 protein." (PMID 24428911, 2014). "Recent studies have demonstrated that the EGFR-TKI gefitinib and erlotinib are associated with a high response rate and prolong progression-free survival in patients with EGFR mutant lung cancer." (PMID 24939055, 2014).
lung cancer (continued). "For instance, the average responses to erlotinib among patients with EGFR-mutant lung cancer and vemurafenib for patients with BRAF V600E mutant melanoma are 11 months and 5 months, respectively." (PMID 25198155, 2014). "Our most recent studies on the UVB (280 nm) illumination of lung cancer cells overexpressing EGFR confirm our predictions (paper in preparation)." (PMID 25386651, 2014). "The finding that STMN3 gene is a downstream target of the ID1, and responds to signaling from nAChRs and EGFR in lung cancer cells is relevant for various reasons." (PMID 25028095, 2014). "Using patient-derived material, we observed that strong SRSF2 over-expression in NSCLC is associated with splicing alterations of the HER1/EGFR and VEGFA transcripts, as predicted from the results in the SRSF2-over-expressing H358 lung cancer cell line." (PMID 24428911, 2014). "In particular, miR-7 emerged as a critical modulator of a regulatory network for EGFR signaling in lung cancer cells, with the ability of coordinately downregulating the expression of several members of the EGFR signaling cascade." (PMID 25250326, 2014). "Nevertheless, an increased EGFR gene copy number has recently been proposed as predictor of anti EGFR targeted therapies in lung cancer patients." (PMID 25227424, 2014). "In another study using constitutive transgenic expression of EGFR L858R in mouse lung, afatinib treatment between weeks 11 and 15 completely prevented the development of lung cancer." (PMID 24643470, 2014). "There is a recent study showing that metformin synergizes with another EGFR inhibitor gefitinib in lung cancer cell lines." (PMID 25361177, 2014). "Thus, early detection of the EGFR mutation rate and its associated factors in lung tumors may present an important reference to individualize clinical treatment and improve treatment implementation in lung cancer, as well as to reduce the toxicity of drugs." (PMID 25013503, 2014). "Accordingly, the inhibition of miR-7 expression suppressed EGFR mRNA and protein expression in different lung cancer cell lines as well as the growth of the A549 lung adenocarcinoma cells." (PMID 25250326, 2014). "Preclinical results show that BIBW2992 is effective in lung cancer models, including those with EGF receptor (EGFR) mutations resistant to reversible first-generation EGFR inhibitors." (PMID 25238247, 2014). "Several small molecule tyrosine kinase inhibitors (TKIs) such as the anti-EGFR targeted drug gefitinib and erlotinib have been tested in clinical trials with some clinical success in lung cancer." (PMID 24625581, 2014). "Oncogenic alterations of epidermal growth factor receptor (EGFR) signaling are frequently observed in lung cancer patients with worse differentiation and poor prognosis." (PMID 24658031, 2014). "The lack of established therapeutic options for patients after a failed EGFR-TKI treatment poses a great challenge to physicians in managing this group of lung cancer patients." (PMID 25610713, 2014). "The discovery of the correlation of EGFR mutations and response to EGFR TKI therapy has demonstrated that molecular typing of tumors to guide therapy selection for lung cancer is possible." (PMID 25608887, 2014). "Crizotinib activity has been reported in MET-amplified tumors, with ongoing studies in EGFR TKI-resistant lung cancer of MET and HGF-targeted agents, such as ficlatuzumab (anti-HGF monoclonal antibody, NCT02034981)." (PMID 25505733, 2014). "EGFR, which is also known as ErbB1 and HER1, is one of the most extensively studied proteins, and plays key roles in many cancers, including colorectal and lung cancer." (PMID 24710267, 2014). "This approach has led to the identification of a broad spectrum of resistance mechanisms arising during inhibition of EGFR in lung cancer and during inhibition of BRAF in melanoma." (PMID 25198155, 2014).